CXCL9 (C-X-C motif chemokine ligand 9)
Diseases named in the same sentence as CXCL9 in open-access papers (continued):
Sharing a sentence is not in itself a finding about the gene and the disease.
infection (continued). "CXCL10 expression is sharply upregulated upon infection and, like fellow chemokine CXCL9, binds receptor CXCR3 expressed on monocytes, NK cells, and T cells to promote their homing to the site of infection." (PMID 30167845, 2018). "Considering that S. pneumoniae-infected mice exhibited significantly greater serum levels of IFN-β, IFN-γ, CXCL9, and CXCL10 than S. aureus-infected mice, we explored the power of these four biomarkers to discriminate between the two infection groups." (PMID 29988532, 2018). "In particular, the levels of I-TAC (CXCL11), IP-10 (CXCL10), MIG (CXCL9), and MCP-3 (CCL7) increased nearly 6-fold upon infection." (PMID 30467502, 2018). "Compared with PBS controls, sublethal infection also markedly induced mRNA levels of TLR2, IFN-γ, TNF-α, CXCL9, CXCR3, and Ang2." (PMID 28742087, 2017). "CXCL9/10, which are IFN-inducible chemokines, are required for effector CD8+ T cell recruitment into sites of infection and for the amplification of immune responses." (PMID 28751894, 2017). "Next, we confirmed that the reduction of CXCL9 and CXCL10 reduced the entry of effector T cells into the infection site." (PMID 28751894, 2017). "The chemokines CXCL9 and CXCL10 have been shown to facilitate entry into the epithelium during infection of mucosal surfaces with HSV-2." (PMID 28407741, 2017). "Multifunctional Th17 cells (IFN-γ+IL-17A+) co-expressing CXCR3/CCR6 are known to upregulate the ligands for CXCR3 (CXCL9/CXCL10/CXCL11) on the lung parenchymal cells, which helps to recruit Th1 cells to the site of infection." (PMID 28985739, 2017). "The chemokines CXCL9 and CXCL10 have been shown to facilitate entry of T cells into epithelium during infection of mucosal surfaces with HSV-2." (PMID 28407741, 2017). "We found mRNAs of the type 1 chemokine ligands and their receptors (CCL4, CCL5, CCR5, CXCL9, CXCL10, CXCL11 and CXCR3) were increased at 21–28 days post-infection compared to uninfected controls." (PMID 28103263, 2017). "CXCR3 and its ligands (CXCL9, CXCL10, CXCL11) are thought to govern the recruitment of leukocytes to the sites of inflammation and infection." (PMID 27068264, 2016). "Among them, CXCL9, CXCL10, and CXCL11 were elevated more significantly following HEP-Flury infection at 4 dpi than CVS-11 infection." (PMID 27242764, 2016). "Seven days post infection, CS + IAV mice had increased mRNA expression of pro-inflammatory chemokines (CCL-2, CXCL-2, CXCL-9, CXCL-10), cytokines (GM-CSF, TNF-α, IL-1β, IL-6) and proteases (MMP-12) compared to sham + IAV + diluent mice or CS + diluent mice." (PMID 26877172, 2016). "Infection activates a broad chemokine response to infection, including CXC (CXCL1, CXCL5, CXCL8, CXCL9, and CXCL10) and CC chemokines (CCL2, CCL3, and CCL5)." (PMID 26927188, 2016). "CHPV infection of PBMC, Monocytes and B cells strongly stimulated the chemokines (CCL2/MCP-1, CCL5/rantes, CXCL9, CXCL10/IP10) during the course of infection." (PMID 27628855, 2016). "Preceding the influx CD3+CD8+ T-cells in this model was an increase in Th1-type chemoattractants CXCL9, CXCL10, CCL3 and CCL5 at peak primary infection." (PMID 27467505, 2016). "Th help was required for enhanced recruitment of CTL to the site of infection in some situations by promoting CXCL9 and CXCL10 production, with CXCL9 being especially important for rapid memory responses in the lymph node." (PMID 26284065, 2015). "The lungs of ECTV-infected Fas- and FasL-deficient mice showed significant inflammation during later phases of infection accompanied by decreased expression of anti-inflammatory IL-10 and TGF-β1 cytokines and disturbances in CXCL1 and CXCL9 expression." (PMID 25873756, 2015). "We have found here that infection with O. tsutsugamushi evoked an early up-regulation of innate IFN-γ, which would promote parenchymal cells to express CXCL9 and CXCL10 chemokines." (PMID 25254971, 2014).
infection (continued). "The infection of MP with MOPV induced robust expression of the CCL2, 3, 4, 5, 7, and 13 genes, and of the CXCL9, 10, and 11 genes, in particular." (PMID 24421914, 2014). "M1-related chemokines CXCL9, CXCL10, and CXCL11 significantly increased after 3 weeks of infection and then declined." (PMID 24666892, 2014). "Microarray analysis revealed that the expression of CCR5, CXCR3 and CCR1 and several of their chemokines including CXCL9, CXCL10, CCL2, CCL3 and CCL9 significantly increases in response to infection in CM-affected mice." (PMID 24476686, 2014). "The T cell chemoattractants CXCL9, CXCL10 and CCL19 are significantly elevated in serum during the acute infection but largely return to normal levels following treatment, resolution of the erythema migrans and recovery." (PMID 24740099, 2014). "Elevated levels of CCL3, CCL4, CCL5 and CXCL9 mRNA were detected in the livers of both WT and WSX-1−/− mice on day 7 of infection, whereas CCL3, CCL4, CCL5 and CCL20 mRNA levels were increased on day 14 of infection." (PMID 24244314, 2013). "Accordingly, mice were orally inoculated with cysts, and relative levels of CXCR3, CXCL9 and CXCL10 mRNA expression were measured over the course of acute infection." (PMID 24130498, 2013). "IEC isolated from neonates at the peak of the infection presented a clear up-regulation of XCL1, CCL3, CCL4, CCL5, CXCL9, and CXCL10 expression, with levels close to those in adults for CXCL9 and CXCL10." (PMID 24367259, 2013). "To further check how Fas and FasL influence the cytokine and chemokine production in vivo we assessed vaginal lavages for the production of chemokines (CXCL1, CXCL9 and CXCL10) and interleukins (IL-1β and TNF-α) at 3 and 7 day of infection." (PMID 23922974, 2013). "Expression of Cxcl9 and Ccl8 was significantly up-regulated in CDC1551-infected cells at both 6 and 24 hpi, compared to infection by HN878, while Il1β was more highly up-regulated at 6 hours than at 24 hours." (PMID 22280836, 2012). "Some others such as CCL3, CCR5, CXCL9, CXCL10, CX3CR1 and CCL24 showed a low expression during the infection." (PMID 22905138, 2012). "The upregulation of ISGs (i.e. CXCL9, IRGM1, PSMB9, STAT1 and UBD) in DBA/2 compared to C57BL/6 mice was confirmed by RT-qPCR at all days post-infection." (PMID 23006927, 2012). "CXCL9 and CXCL10 levels in vaginal washes were significantly different after infection with our different strains." (PMID 21283640, 2011). "For example, genes that encode for CXC-chemokines such as CXCL1 (Gro-α), CXCL5 (Ena-78) and CXCL9 (MIG) were significantly induced at D12 and were induced to higher levels on D15 and D21 post infection." (PMID 21249199, 2011). "Levels of the cytokine IL-6 and of the chemokines CXCL9, CXCL10, and CCL4 were significantly lower in vaginal washes one day after infection with HSV-2/gD compared with HSV-2/gD-Δ7-15." (PMID 21283640, 2011). "In the present study, our goal was to begin to learn how infection with B. burgdorferi stimulates monocytes/macrophages to secrete CCL2, CCL4, CXCL9, and CXCL10." (PMID 20828409, 2010). "Following infection significant increases of CCL2 (MCP-1), CCL3 (MIP-1α), CCL4 (MIP1-β), CCL5 (RANTES) and CXCL9 (MIG) were observed in WT NOD mice compared to uninfected controls." (PMID 19122812, 2009). "While Cxcl9, Cxcl10 and Cxcl11 were upregulated, CXCR3 was downregulated post PCN033 infection." (PMID 41295668, 2025). "Concomitantly, genes involved in inflammatory and interferon-related responses, including IFN-γ, IL-12b, STAT1, STAT3, IL-6, TNF-α, CXCL9, CXCL10, and CXCL5, were significantly upregulated, indicating a strong pro-inflammatory environment during peak infection." (PMID 40630939, 2025). "The DEGs involved in cytokine signaling were upregulated following infection with RHDV2 and included inflammatory cytokines such as IL1α, IL-6, and IL-8, and chemokines such as CCL2, CXCL9, and CXCL11, which were significantly upregulated compared with the non-infected rabbits." (PMID 38675838, 2024).
infection (continued). "As T-cell cytokines in S. aureus-infected bone exhibit a late activation pattern typically observed between 7 and 14 days post-infection, we did not assess the expression of CXCL9/10 in T cells by day 3 post-infection in our study." (PMID 39001897, 2024). "We broadly confirmed a decrease in inflammatory genes, including Ccl1, Cxcl9, Tnf, and Ifnb1, among others, in infected Gsdmd−/− versus WT mice, while no baseline differences were observed in the absence of infection." (PMID 38553499, 2024). "Serving as chemokines, CXCL9, CXCL10, and CXCL11 attract the cells with their cognate receptor CXCR3, including neutrophils, monocytes/macrophages, dendritic cells, T cells, and NK cells, to the site of infection." (PMID 37214455, 2023). "Similarly, while SARS-CoV-2 infection alone induced a minimal expression of the inflammatory chemokines, the IAV single-infection group induced significantly high levels of CCL3, CCL4, CCL5, and CXCL9." (PMID 35107382, 2022). "MIG/CXCL9 and IP-10/CXCL-10, also named “interferon-inducible CXC chemokine receptor 3 ligands”, are ELR-negative CXC chemokines induced by IFN-γ or other stimuli during infection or inflammation in several immune cell." (PMID 36466710, 2022). "For example, heat-iMVA infection triggered higher levels of IFN-inducible genes than MVA, including Ifih1 (MDA5), Ddx58 (RIG-1), Oasl2, Oas3, TLR3, Nod1, Ifna4, Ifnb1, Ccl5, Cxcl9, Cxcl10, and members of the guanylate binding protein (Gbp) family, as largely dependent on STING (marked as b)." (PMID 36261460, 2022). "Additionally, IFN-γ, which is essential for the expression of CXCL9 and CXCL10 by macrophages and several cell types during the recruitment of T-cells at the site of infection, is produced to enhance host protection." (PMID 36189358, 2022). "In contrast, the downregulation of RANTES/CCL5, MIP-1α/CCL3, and MIP-1β/CCL4 from the early to middle phase of the infection as well as the downregulation of MIG/CXCL9, IP-10/CXCL10, and IL-13 in the middle phase of the infection were observed in aged BALB/c mice." (PMID 35264719, 2022). "This study assesses the value of the CXCR3 ligands CXCL9/MIG, CXCL10/IP-10 and CXCL11/I-TAC when used to supplement the standard infection markers C-reactive protein (CRP) and procalcitonin (PCT) in the diagnostic algorithm of neutropenic fever in children with cancer." (PMID 36670590, 2022). "Heightened colonic cytokine levels in the WT-infected group also correlated with significant increases in serum GCSF, IL-1β, IL-3, IL-6, IL-17, CXCL1, CXCL9, MCP-1, TNF-α and TREM at the peak of infection (48-hours), when compared to the TcdA−TcdB−CDT+ and uninfected groups (p< .05)." (PMID 36045589, 2022). "Mincle-/- cells also produced less Nos2, Tnfa, Il27, and Cxcl9 than WT cells upon infection, but the reduction did not meet statistical significance under the tested infection doses and time." (PMID 34320039, 2021). "Interestingly, neuropathic strains of EHV-1 have been shown to selectively stimulate CXCR3 ligands CXCL9 and CXCL10 production by the respiratory epithelium to facilitate attraction and infection of CD4, CD8, and monocytic CD172+ cells." (PMID 34179166, 2021). "Furthermore, influenza virus has been shown to induce rapid the expression of CXCL9 and CXCL10 following infection in epithelial cells." (PMID 34179166, 2021). "LY3214996- and Dactolisib-treated cells displayed less pronounced reductions in CXCL9 induction, while PD98059 and JNK-IN-8 did not statistically reduce CXCL9 transcript levels following infection." (PMID 34205098, 2021). "Interestingly, P18 deletion led to a significant upregulation of both CXCL9 and 10, suggesting the recruitment of T cells to mount the needed IFN-γ immune response to control the infection." (PMID 34262559, 2021). "In addition, patients with acute toxoplasmosis showed significantly higher plasma levels of CCL4, CXCL9, and CXCL10 than patients in the chronic phase of infection or HDs." (PMID 34607465, 2021).
infection (continued). "In contrast, for all analyzed mouse strains no vaccine-induced increase in Cxcl9 expression was observable at week 2 post-infection." (PMID 34351501, 2021). "infection or transverse the BBB attracted by CXCL9 and CXCL10 during the late stage of infection." (PMID 34587172, 2021). "Similar to the “cytokine storm”, inflammatory chemokines like CXCL9 and CXCL10 are likely important to mount an effective immune response to the parasite early during the infection, but may be detrimental under certain circumstances." (PMID 33407502, 2021). "CXCL9, CXCL10, and CXCL11 are chemokines which are able to induce chemotaxis in CD4+ Type-1 helper (Th1) and CD8+ cytotoxic lymphocytes as well as in natural killer cells and natural killer T cells, directing them to sites of infection and inflammation." (PMID 32328494, 2020). "Importantly, CXCL10, CXCL9 and CCL5 were produced throughout the course of infection (until day 120), even when tissue parasitism was low." (PMID 32393333, 2020). "Infection with H. felis led to Cxcl9 up-regulation only in Myd88−/− mice after 25 and 47 weeks of infection, while no induction was detected in WT animals." (PMID 31065023, 2019). "In fact, results from a recent study demonstrated that peripheral infection with WNV increased CNS expression of chemokines important for lymphocyte trafficking, including CCL2, CCL7, CXCL9, and CXCL10, in PLX5622-treated mice compared with control-treated mice." (PMID 30704498, 2019). "Amongst cytokines, the genes for Cxcl9, Cxcl10, Cxcl13, Il-1β, Il-6, Tnf, Tnfsf10, IFN-γ, Ccl2, Ccl4, Ccl7, Ccl17, and Mif were highly up-regulated (ranging from 2- to 405-fold, p ≤ 0.05), whereas Cxcl12 and Cxcl14 were down-regulated during in vivo infection." (PMID 30857242, 2019). "Similar to airway epithelial cells, human macrophages express type I and type III IFNs, IL-1α, IL-1β, IL-6, TNF-α, CXCL8, CCL2 (MCP-1), CCL3 (MIP-1α), CCL4 (MIP1-β), CXCL9, and CXCL10 following infection with seasonal H1N1 or with H5N1, 2009 H1N1 strains demonstrating increased pathogenicity." (PMID 29623073, 2018). "Regarding the chemokines, diverse studies in humans and mice have indicated that CXCL1, CXCL9, CXCL10, CCL2, CCL3, CCL4, and CCL5 are important in controlling the infection during the acute phase, and the levels of virtually all of them were increased in both BALB/c and C57BL/6 mice." (PMID 29662478, 2018). "We confirmed a productive infection of HSV-2 in mouse vagina by immunohistochemistry and immunofluorescence-histochemistry assays, while Cytometric Bead Array (CBA) showed that the production of mouse chemokines CXCL9 and CXCL10 was significantly increased." (PMID 30619292, 2018). "Both groups exhibited a significant increase in expression of CXCL9 and CXCL10 during the infection which could be correlated with the levels in T cell and monocytes." (PMID 30248353, 2018). "Severe IV infection induces many cytokines; IFNαβ, TNFα, IFNγ, C-X-C motif chemokine (CXCL) 10 (CXCL10), CXCL9, C-C motif ligand (CCL) 2 (CCL2), CCL4, CCL5 and interleukin (IL)−6 (IL-6), IL-2, IL-8, and IL-10 have all be observed to be upregulated during severe IV infection in humans." (PMID 30250466, 2018). "Expression of an array of cytokines (CSF3 [G-CSF], IFNγ, IL-1β, IL-6, IL-22, IL-17A, and IL-10), chemokines (CCL20, CXCL2 and CXCL9) and receptors (CD40) known to be involved in the regulation of S. pneumoniae inflammatory response was measured at 0, 6, 24, and 48 h post-infection." (PMID 30333823, 2018). "The genes with strongest induction included chemokines (e.g. CXCL11, 84-fold; CXCL10, 18-fold; CXCL9, 9-fold; CCL2, 9-fold) and cytokines (e.g. IL6, 54-fold; IL12B, 10-fold; IL1B, 9-fold;) etc. consistent with the infection of host phagocytes with Mtb reported earlier by us." (PMID 28880895, 2017).
infection (continued). "Given the marked elevation of transcripts for proinflammatory cytokines (IFN-γ and TNF-α) and T-cell recruiting signals (CXCL9 and CXCR3) in infected brains, we decided to focus on lethal infection, especially vascular/cellular activation and leukocyte recruitment." (PMID 28742087, 2017). "CXCR3 and its ligands, CXCL9, CXCL10, and CXCL11, play a pivotal role in the regulation of inflammatory and infectious diseases, in which CXCR3-bearing effector leukocytes are recruited to the sites of inflammation or infection." (PMID 27068264, 2016). "The selected targets included genes that were differentially expressed in both gt1‐ and gt3‐infected samples versus controls (CXCL9, IFIT1, ISG15 and RSAD2), as well as genes that were differentially regulated only in gt1 infection (USP18) or gt3 infection (IDO1)." (PMID 25800823, 2015). "Activated Th1 CD4 T cells and effector CD8 T cells express this receptor, and promote migration of activated CD8 T cells into non-lymphoid tissue infection sites under the influence of the chemokine ligands CXCL9 and CXCL10." (PMID 26322025, 2015). "Neutrophils that are primarily recruited by CXCL8 can exert antiviral immunity amongst others by the release of inflammatory cytokines (e.g., IL-12, TNFα) and chemokines (e.g., CCL2, CXCL8, CXCL9, CXCL10) that leads to further recruitment of immune cells to the site of infection." (PMID 24646914, 2014). "The infection of MP with rNP LASV led to a robust and significant increase in the synthesis of CCL2, 4, 5, and 7, and of CXCL9, 10, and 11 mRNA and to a strong release of these chemokines in the culture supernatants, as shown by comparison with mock-infected cells." (PMID 24421914, 2014). "By contrast, CXCL9 mRNA levels were not significantly affected by infection with either virus (data not shown)." (PMID 24421914, 2014). "Furthermore, another group reported that the CXCR3 ligands, CXCL9, CXCL10 and CXCL11, were induced markedly at the levels in the spleen, lung, and liver following infection with T. gondii." (PMID 24661782, 2014). "Expression of CXCL9 and 10 can be induced by IFN-γ and/or TNFα in several liver resident cells, including hepatocytes, LSECs, HSCs and KCs, promoting further recruitment of CXCR3-expressing cells to the site of infection." (PMID 24646914, 2014). "Although it is unclear how these cells migrate to the intervillous space during infection, it is possible that recruitment of B and T cells may be mediated by CXCL13 and CXCL9 respectively." (PMID 24476686, 2014). "In the same work, CXCL9/MIG, IP-10, and high titers of IgG were found in patients with mild and severe symptoms six months after initial infection when compared to recovered patients, suggesting that these factors may be used as disease severity markers." (PMID 24069610, 2013). "First of all, down-regulation of FCN1, CXCL9 and SEPP1 may prevent early local innate immune responses against the virus allowing infection and replication." (PMID 23383108, 2013). "Following infection by C. parvum sporozoites in vitro, the mouse epithelial cell line CMT-93 upregulated CXCL9 and CXCL10 24 h later suggesting that independently of IFNγ, IEC can in some conditions upregulate these chemokines in direct response to the parasite." (PMID 24367259, 2013). "In addition, PR/8 infection up-regulated mRNA expression of many chemokine genes including CC chemokines CCL2–5, and CCL20, as well as CXC chemokines CXCL9–11." (PMID 22396727, 2012). "CXCL10 and CXCL9 were found to be significantly increased in the patients with mild and severe symptoms at 6 months following initial infection compared to the patients reporting no symptoms." (PMID 21858242, 2011). "Increased expression of CXCL9, CXCL10, and CXCL11 suggests either that IFN-γ induces the expression of these chemokines or that Type I interferons are increased during the first 12 hours of infection in the bovine intestine." (PMID 22096503, 2011).